EPO (erythropoietin)
Diseases named in the same sentence as EPO in open-access papers (continued):
Sharing a sentence is not in itself a finding about the gene and the disease.
ischemic stroke (continued). "Furthermore, pre-clinical studies comparing the doses, routes, and times of EPO administration in ischemic stroke models are essential for its clinical translation." (PMID 35250554, 2022). "The therapeutic effects of EPO treatment for ischemic stroke have been widely studied." (PMID 35250554, 2022). "The safety and efficiency of EPO derivatives for ischemic stroke remains unclear and is warranted further exploration." (PMID 35250554, 2022). "Therefore, the intracerebral transplantation of EPO‐producing fibroblasts benefited an ischemic stroke model, probably via the enhancement of neurogenesis." (PMID 30920178, 2019). "Furthermore, EPO enhances angiogenesis and neurogenesis after ischemic stroke, leading to accompanying functional recovery." (PMID 31024439, 2019). "Therefore, in this study, we attempted to use a fibroblast cell line as a carrier and transplant EPO‐producing fibroblasts directly into the infarcted brain of a rodent model of ischemic stroke." (PMID 30920178, 2019). "Here, we hypothesized that neuroprotection after ischemic stroke by EPO and GRINA could be mediated by the regulation of the post-ischemic UPR and in particular by the IRE1α and PERK pathways of the UPR." (PMID 31683519, 2019). "In addition, EPO also increased the number of newly generated oligodendrocytes and attenuated the rapid hypertrophy and hyperplasia of microglia and astrocytes after ischemic stroke (P<0.05)." (PMID 28840056, 2017). "However, recent reports have demonstrated that EPO plays a neuroprotective role in the central nervous system, and EPO has been considered as a therapeutic target in neurodegenerative diseases such as ischemic stroke." (PMID 28817120, 2017). "Therefore, we investigated a novel therapeutic approach based on EPO's cytoprotective effects, using an ischemic stroke model induced by platelet-rich thrombus." (PMID 27248662, 2016). "In addition, it was shown that erythropoietin-transduced human mesenchymal stromal cells (EPO-MSCs) played a neuroprotective role in the rat model for ischemic stroke." (PMID 21776259, 2011). "Finally, advanced studies of the therapy of EPO derivatives in ischemic stroke were also discussed." (PMID 35250554, 2022). "Therefore, EPO may be a promising therapeutic agent to enhance hUCBC treatment in ischemic stroke to induce neurogenesis and angiogenesis." (PMID 31024439, 2019). "However, it is unknown whether this effect extends to adult mice and whether EPO regulate microglia polarization after ischemic stroke." (PMID 28840056, 2017). "However, the effects of EPO on microglial polarization, oligodendrogenesis and white matter integrity after ischemic stroke in adult mice are currently unknown." (PMID 28840056, 2017). "Therefore, it was speculated that EPO administration might constitute a promising therapeutic approach in brain disorders, such as ischemic stroke." (PMID 27248662, 2016). "When injected before ischemic stroke or during reperfusion, effectiveness of EPO reveals a larger therapeutic time-window when compared to rtPA, thus suggesting that rhEPO administration should be an effective treatment with a large time window following ischemic stroke, at least in young patients." (PMID 27248662, 2016). "In mice, EpoR expression increased with ischemic stroke along with increased EPO production, and EPO treatment reduced infarct size, suggesting that in ischemic injury, EpoR increases EPO response and the increase of EPO availability contributes to neuroprotection." (PMID 22567318, 2012). "Optimized versions of EPO and LTF have shown experimental evidence of neuroprotective effects in ischemic stroke and intracerebral hemorrhage." (PMID 41266628, 2025). "After adjustment for all potential confounding factors, the use of EPO was found to be an independent predictor of successful transdural revascularization, suggesting that this combination therapy could be applied to the acute setting of ischemic stroke with perfusion impairment." (PMID 35579016, 2022).
ischemic stroke (continued). "This study tested the superiority of combined cyclosporine A (CsA)-erythropoietin (EPO) therapy compared with either one in limiting brain infarction area (BIA) and preserving neurological function in rat after ischemic stroke (IS)." (PMID 21864394, 2011). "In a previous study body fluid biomarkers for brain damage after ischemic stroke including S100B, glial fibrillary acid protein (GFAP) and ubiquitin C-terminal hydrolase (UCH-L1) were significantly lower in the EPO treated patients than in placebo treated ones." (PMID 40791908, 2025). "EPO showed potential for treatment of ischemic stroke in a Phase I clinical trial, but the beneficial effect of EPO administration in ischemic stroke was not realized in an expanded Phase II/III clinical trial." (PMID 38628440, 2024). "CEPO, one of EPO derivatives, was proved safe in healthy volunteers and improved cognitive functions in PD patients, while it has not been studied in ischemic stroke patients." (PMID 35250554, 2022). "In a clinical trial, EPO administration after ischemic stroke improved clinical recovery and brain damage in patients not receiving thrombolysis." (PMID 32733466, 2020). "Erythropoietin (EPO) can enhance neurogenesis and fibroblasts can secrete growth factors; together, they may benefit ischemic stroke." (PMID 30920178, 2019). "As EPO can cross the blood-brain barrier (BBB), it has been reported that systemic administration of EPO may reduce neuron damage in animal models of ischemic stroke, traumatic brain injury, and spinal cord injury." (PMID 24939444, 2014). "Notably however, the observed reduced mRNA expression of the neuroprotective growth factors EPO and VEGF-A in P4htm−/− mice under ischemic stroke may add to the increased MCAO-induced neuroinflammation in these mice relative to WT." (PMID 35151685, 2022). "In the last few years, non-haematopoietic EPO analogues, which include asialoerythropoietin (asialoEPO), carbamylated EPO (CEPO), and rHU-EPO with a low sialic acid content (neuroEPO) that do not exhibit erythropoietic activity, have been tested in the treatment of ischemic stroke." (PMID 29438293, 2018). "Our finding of high EPO and EpoR mRNA levels in the brain and our demonstration of the hypoxic upregulation of both of these proteins are suggestive of the mechanisms through which the EA therapeutic modality at GV20 and ST36 may contribute to ischemic stroke." (PMID 28848617, 2017). "New non-haematological EPO agents have been developed primarily for treatment of ischemic stroke." (PMID 19521513, 2009). "However, it has been reported that EPO exacerbates cerebral oedema, BBB leakage, and extracellular matrix breakdown in thrombolysed mice, suggesting that ischemic stroke patients may be potential candidates for rhEPO treatment, when not suitable for thrombolysis." (PMID 27248662, 2016). "However, to our knowledge, the influence of exogenous EPO on ER stress and UPR and especially the involvement of EPO in the UPR after ischemic stroke has not been investigated yet." (PMID 31683519, 2019).
malaria (44 papers, 2005 to 2025). Malaria is a serious and sometimes fatal disease caused by a parasite that commonly infects a certain type of mosquito which feeds on humans. "Malaria causes increased destruction and removal of both infected and uninfected erythrocytes, decreases erythrocyte production, and suppresses the erythropoietin response, all contributing to malarial anemia." (PMID 39364186, 2024). "This byproduct, generated via hemoglobin digestion, is likely associated with an increase in EPO production and effectivity during malaria." (PMID 38892340, 2024). "During blood stage malaria, EPO production by the kidney increases to counteract the loss of red blood cells." (PMID 27441662, 2016). "Acute clinical malaria has been associated with a reduction in STfR measurement and a rapidly reversible suppression of bone marrow response to EPO." (PMID 18461143, 2008). "However, the importance of endogenous circulating EPO levels has also previously been shown in children with malaria where high EPO levels were associated with a reduced risk of neurological sequelae." (PMID 35462689, 2022). "This study is however limited by the small sample size used which may have encumbered the full exploration of the association between anti-EPO and malaria." (PMID 30894794, 2019). "In human studies, severe malaria has been associated with increased angiopoietin-2, decreased angiopoietin-1, and decreased endothelial nitric oxide levels, and the upregulation of counter-regulatory molecules including HO-1 and erythropoietin." (PMID 23696730, 2013). "Interestingly, the inhibition of BM erythropoiesis in patients infected by P. falciparum or in mice infected with rodent malaria parasites occurs despite increased levels of EPO in blood, suggesting that Plasmodium infection causes suppression of the BM response to EPO." (PMID 36361552, 2022). "Additionally, the duration of the infection has been associated to the clinical profile of malaria, suggesting that this parameter could be related to EPO." (PMID 21912616, 2011). "In mice, EPO stimulation has been shown to improve animal survival in response to malaria, enhancing RBC production and reducing hypoxia, iron (Fe) cytotoxicity, and tissue damage." (PMID 38892340, 2024). "Hormones such as DHEA, melatonin, PTH, Vitamin D3, hepcidin, progesterone, and erythropoietin protects against malaria." (PMID 39492784, 2024). "Higher concentrations of EPO were found in reinfected mice to be already at the basal level and increasing significantly during malaria." (PMID 38892340, 2024). "Exogeneous administration of hormones like DHEA, melatonin, PTH, Vitamin-D3, hepcidin, progesterone and erythropoietin have been reported to protect against malaria pathologies." (PMID 39492784, 2024). "Chloroquine reduces erythropoietin levels in healthy individuals but enhances it in malaria patients." (PMID 39492784, 2024). "The higher P. falciparum parasite density identified among the pregnant women with anti-EPO antibodies in this study suggests a possible contribution of parasitaemia to the development of the antibody in malaria." (PMID 36989322, 2023). "EPO-sensitive erythropoiesis is obviously also critical for the outcome of P. chabaudi blood-stage malaria." (PMID 31996238, 2020). "Erythropoietin concentration was significantly higher in malaria-related anaemic subjects (p=0.032)." (PMID 30894794, 2019). "In this study, majority of the participants with malaria were found to be anaemic (59.6%); and EPO concentration was significantly higher in malaria-related anaemic subjects compared to their nonanaemic counterparts." (PMID 30894794, 2019). "Venous blood was collected for thick and thin films for malaria microscopy, full blood count by automated haematology analyzer, and antierythropoietin antibody and erythropoietin estimation by sandwich ELISA method." (PMID 30894794, 2019).
malaria (continued). "We found an increase in EPO levels in the plasma of P. falciparum-infected patients from Odisha with severe malaria, and particularly with fatal CM." (PMID 27441662, 2016). "Given our findings on the heme/hemopexin balance that influences cytokine profiles during severe malaria, we first investigated a possible correlation between EPO, TNF-α, IL-10, IP-10 and MCP-1 plasma levels." (PMID 27441662, 2016). "We found a significant increase in EPO levels with malaria severity degree, and more specifically during fatal CM." (PMID 27441662, 2016). "In conclusion this study has confirmed earlier findings that erythropoietin production is age-related with younger children having the ability to produce more erythropoietin during acute malaria than older children." (PMID 25138388, 2014). "The objective of the study was to evaluate anti-EPO antibody levels in anaemic condition of different strains of semi-immune mice with malaria." (PMID 23978045, 2013). "Animal models of malaria suggest that erythroid suppression is further exacerbated by a reduced response of progenitor cells to erythropoietin." (PMID 23282136, 2013). "Assessment of EPO levels in our group of mice at the day of euthanasia revealed significantly higher EPO concentrations in mice with acute malaria, and comparable levels in naive, bled and PHZ-treated mice." (PMID 23029401, 2012). "According to the results, SM cases presented the highest levels of EPO among the study groups and EPO levels increased progressively with malaria severity." (PMID 21912616, 2011). "In the present study, we have assessed the relation between EPO and malaria-attributable severe disease among children with malaria (uncomplicated, hospitalized without severity and severe) or severe infection (severe malaria and bacteremia)." (PMID 21912616, 2011). "This study assessed the relation between erythropoietin (EPO) and malaria-attributable severe disease in an area of Mozambique with moderate malaria transmission." (PMID 21912616, 2011). "Other potential vasomodulatory pathways have been examined in the severe malaria, such as tumour necrosis factor, angiopoetin, erythropoietin and nitric oxide." (PMID 21923924, 2011). "A certain degree of EPO unresponsiveness has also been found in malaria-infected mice." (PMID 38892340, 2024). "Moreover, artesunate-erythropoietin treatment has been shown to induce early recovery from P. berghei induced malaria as compared to artesunate mono-treatment." (PMID 39492784, 2024). "The data, therefore, suggest that EPOR-mediated EPO sensitivity by hepatic erythroblasts precedes EPO production in the liver, and that malaria-induced erythroblastosis in the liver may require hepatic EPO particularly at peak parasitaemia." (PMID 31996238, 2020). "There are, however, conflicting reports on levels of EPO during episodes of malaria." (PMID 30894794, 2019). "EPO concentration was significantly higher in malaria-related anaemic subjects (p=0.032)." (PMID 30894794, 2019). "There are contradictory reports on whether the erythropoietin response is adequate in symptomatic malaria patients mainly due to methodological issues in older studies." (PMID 31792345, 2019). "Relevantly, macaques that had been malaria naïve when infected exhibited erythropoietin levels that were elevated six-fold during periods of high parasitaemia, indicating that ineffective erythropoiesis is not mediated by the dysregulation (i.e., lack) of compensatory erythropoietin production." (PMID 27520455, 2016). "All four cytokines were positively correlated to EPO levels during malaria, as well as to CM cases." (PMID 27441662, 2016). "However, the utility of EPO to distinguish malaria-attributable severe disease has been questioned due to the overlap of EPO values between children with severe malaria and invasive bacterial infection." (PMID 26979504, 2016).
malaria (continued). "Other than age, distinct environmental determinants such as the genetic background and hematological parameters may also influence the pathophysiology of CM, and consequently the role of EPO in the outcome of malaria." (PMID 27441662, 2016). "In fact, molecules released during parasite multiplication within red blood cells, such as heme, may contribute to increased EPO levels during malaria." (PMID 27441662, 2016). "Hence, EPO seemed to act differently on the cerebral than the systemic regulation of VEGF since plasma VEGF was increased in EPO-treated malaria mice." (PMID 24995009, 2014). "There was a significantly negative correlation between levels of haemozoin-containing monocytes and EPO, which may suggest that haemozoin suppresses erythropoiesis in severe malaria." (PMID 25138388, 2014). "In this study we correlated the levels of erythropoietin (EPO), as an indicator of stimulation of haemoglobin production, to the levels of monocyte acquired haemozoin in children with both severe and uncomplicated malaria." (PMID 25138388, 2014). "Whereas EPO ameliorates hemolytic anemia in malaria or trypanosomiasis and improves the course of autoimmune diseases such as inflammatory bowel disease or autoimmune encephalomyelitis, it deleteriously inhibits macrophage functions in Salmonella infection in animal models." (PMID 22094132, 2012). "Several studies have described high levels of EPO in African children with malaria, suggesting that EPO might be a good indicator of malaria-attributable disease." (PMID 21912616, 2011). "Although our previous studies in these severe malaria cases have demonstrated hypoxic-associated protein expression of EPO and its receptors, this was not the case for VEGF and its receptors." (PMID 20716170, 2010). "However, it cannot be excluded that hepatic EPO may be also involved in the stimulation of other processes in the liver, which are important to survive blood-stage malaria." (PMID 31996238, 2020). "Erythropoietin (EPO), a glycoprotein hormone principally produced by the kidney’s peritubular capillary endothelial cells in response to hypoxia, has been shown to be increased in African children with malaria, suggesting that EPO might be a good indicator of malaria-attributable disease." (PMID 26979504, 2016). "A number of adjunctive therapies (including nitric oxide, arginine, erythropoietin, levamisole) have demonstrated encouraging results in experimental models of cerebral malaria or in clinical trials in uncomplicated malaria and are awaiting evaluation in severe malaria." (PMID 21772838, 2012). "However, deficient erythropoietin production does not appear to be the cause of inadequate erythropoiesis in malaria." (PMID 22624872, 2012). "Nevertheless, some studies have suggested the use of biomarkers in Africa for purposes other than clinical diagnosis, whether EPO combined with other parameters could increase the specificity of severe malaria endpoint in epidemiological studies remains to be explored." (PMID 21912616, 2011). "During the first 15 days of supplementation a decrease in EPO measurement in the non-malaria group was associated with a decrease in STfR measurement whilst in the malaria group a significantly greater drop in EPO measurement was associated with an increase in STfR measurements." (PMID 18461143, 2008). "At concentrations found in the circulation of malaria infected patients, MIF was found to suppress erythropoietin-dependent erythroid colony formation." (PMID 27034825, 2016). "A recent study has shown that treatment with exogenous anti-erythropoietin (anti-EPO) antibodies (Ab) of infected mice gives protection against malaria infection, suggesting an important role for anti-EPO Ab in malaria." (PMID 23978045, 2013). "Serum EPO level was relatively higher among pregnant women with P. falciparum malaria compared to controls without malaria." (PMID 36989322, 2023).